FAM20C (FAM20C golgi associated secretory pathway kinase)
Diseases named in the same sentence as FAM20C in open-access papers (continued):
Sharing a sentence is not in itself a finding about the gene and the disease.
Insulin resistance (2 papers, 2025). Increased resistance towards insulin, that is, diminished effectiveness of insulin in reducing blood glucose levels. "Taken together, these data suggest that elevated FAM20C in VIS AT is strongly associated with insulin resistance and hyperinsulinemia in individuals with obesity." (PMID 41148235, 2025). "Our data support a model where FAM20C serves as an early mediator of obesity-induced inflammatory signaling and insulin resistance in adipocytes, contributing to the progression from obesity to insulin resistance and T2D." (PMID 41148235, 2025). "Fam20c induces a broad proinflammatory gene expression pattern and insulin resistance in adipocytes." (PMID 41148235, 2025). "By regulating key pathways involved in focal adhesion, PI3K/AKT/mTOR signaling, inflammatory response, and lipolysis, FAM20C modulates adipocyte function and contributes to insulin resistance in obesity." (PMID 41148235, 2025). "Adipocyte Fam20c promotes early inflammatory remodeling and insulin resistance during diet-induced obesity." (PMID 41148235, 2025). "Of translational relevance, we showed that in humans, visceral adipose FAM20C expression positively correlates with insulin resistance." (PMID 41148235, 2025). "Together, these findings suggest that Fam20c facilitates early adipose inflammation and systemic insulin resistance during the initial stages of diet-induced obesity." (PMID 41148235, 2025). "Ablation of adipocyte FAM20C also enhanced insulin sensitivity in other metabolic tissues, such as the liver and muscle, placing FAM20C within ATs as a systemic mediator of insulin resistance." (PMID 41148235, 2025). "The adipo-IR index was approximately 40% lower in iAd-Fam20c–KO mice compared with controls (0.75 ± 0.04 vs. 1.24 ± 0.46, P = 0.03), suggesting that Fam20c deletion ameliorates AT insulin resistance." (PMID 41148235, 2025). "Forced expression of Fam20c in adipocytes promoted robust upregulation of proinflammatory cytokines and induced insulin resistance that is dependent on its kinase activity." (PMID 41148235, 2025). "Together, these findings support a direct, kinase-dependent role for FAM20C in promoting adipocyte inflammation and insulin resistance." (PMID 41148235, 2025). "Building on the link between Fam20c upregulation and adipocyte dysfunction, we investigated whether Fam20c directly contributes to insulin resistance." (PMID 41148235, 2025). "Overall, our data not only validate Fam20c as a key mediator of insulin resistance in adipocytes but also suggest that inhibition of Fam20c may serve as a promising therapeutic approach to alleviate obesity-induced metabolic dysfunction." (PMID 41148235, 2025). "Importantly, KO of Fam20c in adipocytes after established obesity and hyperglycemia corrected glucose intolerance and insulin resistance, suggesting that targeting Fam20c could be a potential strategy for restoring adipocyte function and metabolic homeostasis." (PMID 41148235, 2025). "By linking FAM20C kinase to adipocyte inflammation, adipose insulin resistance, and systemic metabolic impairment, we expand the current understanding of molecular pathways that transition obesity into T2D, highlighting adipocyte FAM20C as a potential therapeutic target." (PMID 41148235, 2025). "Collectively, these findings demonstrate that Fam20c regulates VIS WAT expansion and adipocyte size distribution, and its deletion protects against VIS adiposity and obesity-induced insulin resistance." (PMID 41148235, 2025). "In both VIS and SC ATs, FAM20C levels positively correlated with HOMA-IR, a well-established indicator of insulin resistance." (PMID 41148235, 2025). "Taken together, these results suggest that FAM20C-mediated phosphorylation of CNPY4 at Ser64 promotes proinflammatory gene expression and contributes to AT insulin resistance in obesity." (PMID 41148235, 2025).
Insulin resistance (continued). "In our study, FAM20C expression was markedly higher in VIS AT compared with in SC AT, and its levels positively correlated with insulin resistance markers such as HOMA-IR and FPI." (PMID 41148235, 2025).
kidney cancer (2 papers, 2021). Primary or metastatic malignant neoplasm involving the kidney. "Further, in bladder, breast, colorectal and kidney cancer, a lower expression level of Fam20C was found." (PMID 33306121, 2021). "In contrast, decreased expression of Fam20C was found in bladder and kidney cancers." (PMID 33306121, 2021).
multiple sclerosis (2 papers, 2018 to 2020). A progressive autoimmune disorder affecting the central nervous system resulting in demyelination. "Fingolimod, a structural analog of sphingosine and a clinically approved drug for treating multiple sclerosis, also stimulates Fam20C kinase activity." (PMID 29572475, 2018).
Obesity (2 papers, 2024 to 2025). Accumulation of substantial excess body fat. "Further mechanistic studies are needed to elucidate the pathways by which Fam20c selectively impairs obesity-associated VIS WAT expansion." (PMID 41148235, 2025). "This study also revealed an obesity-associated increase in Fam20c across all 6 mouse adipocyte subclusters (mAd1–mAd6) and 1 human adipocyte subcluster (hAd5) that positively correlated with BMI." (PMID 41148235, 2025). "Together, these results suggest that Fam20c upregulation is a conserved, obesity-associated feature of specific adipocyte subtypes in both mice and humans." (PMID 41148235, 2025). "To investigate the potential role of FAM20C in the development of obesity, we generated adipocyte‐specific FAM20C deficient mice by crossing FAM20C flox/flox mice with Adipoq‐cre transgenic mice." (PMID 39532808, 2024). "Our findings suggest that FAM20C is a potential target for treating obesity and associated metabolic disorders." (PMID 39532808, 2024). "The strong induction of Fam20c in adipocytes during obesity led us to examine whether this regulation was linked to specific adipocyte subpopulations by analyzing single-cell and single-nucleus RNA-seq datasets of mouse and human WAT." (PMID 41148235, 2025). "In human WAT, FAM20C expression was substantially enriched in the hAd5 subcluster, and the proportion of hAd5 cells positively correlated with BMI, suggesting an association between FAM20C expression and obesity-driven expansion of specific adipocyte populations." (PMID 41148235, 2025). "Taken together, our results indicate that targeting FAM20C in adipocytes may be a promising strategy for the treatment of obesity and associated metabolic disorders." (PMID 39532808, 2024). "By identifying Fam20c as a key molecular switch in adipocyte dysfunction, our findings provide insights into the mechanisms driving obesity-related metabolic diseases and offer potential therapeutic avenues for preventing or treating T2D." (PMID 41148235, 2025). "Sustained induction of Fam20c across multiple stages of obesity underscores its potential role as an early and persistent driver of adipocyte dysfunction." (PMID 41148235, 2025). "To define the contribution of adipocyte Fam20c to immune cell infiltration during early obesity, we disrupted adipocyte FAM20C after 4 weeks of HFD using inducible iAd-Fam20c–KO and control mice." (PMID 41148235, 2025). "FAM20C is identified as a key mediator of obesity-induced adipocyte dysfunction and inflammation, suggesting its inhibition as a potential therapy for type 2 diabetes." (PMID 41148235, 2025). "We demonstrate that Fam20c expression is upregulated in adipocytes in response to obesity and that its kinase activity drives a proinflammatory gene expression signature." (PMID 41148235, 2025). "We identified FAM20C, a serine/threonine kinase, as an early obesity-induced mediator of adipocyte dysfunction." (PMID 41148235, 2025). "Our study identifies Fam20c, an obesity-induced gene, as an early mediator of adipocyte dysfunction, unveiling its ability to alter both intracellular and extracellular signaling within AT." (PMID 41148235, 2025). "Obesity-induced Fam20c in the VIS WAT phosphorylates proteins involved in adipogenesis and AT dysfunction." (PMID 41148235, 2025). "Fam20c expression was substantially upregulated in adipocytes in response to obesity, correlating with a proinflammatory transcriptional signature." (PMID 41148235, 2025). "With the mild protection from obesity, subtle improvements in glucose tolerance were expected in the constitutive adipocyte Fam20c KO." (PMID 41148235, 2025). "A recent report showed that mice with constitutive KO of adipocyte Fam20c are protected from diet-induced obesity and have slightly improved glucose homeostasis under HFD." (PMID 41148235, 2025). "We found that Fam20c expression was robustly induced early in obesity and was specific to the adipocyte fraction, as Fam20c expression was unchanged in the SVF." (PMID 41148235, 2025).
Obesity (continued). "Conversely, deletion of adipocyte Fam20c after established obesity and hyperglycemia improved glucose tolerance, augmented insulin sensitivity, and reduced visceral adiposity, without altering body weight." (PMID 41148235, 2025). "Overall, our findings pave the way for the development of targeted therapies that modulate FAM20C activity in adipocytes to treat obesity-related metabolic diseases." (PMID 41148235, 2025). "Our findings establish FAM20C as an early regulator of obesity-induced adipocyte dysfunction and systemic metabolic impairment." (PMID 41148235, 2025). "A key finding of our study is that Fam20c expression is significantly and selectively induced in adipocytes in 2 mouse models of obesity and T2D with different dietary compositions." (PMID 41148235, 2025). "Our results suggest that Fam20c plays a pivotal role in regulating VIS WAT expansion in response to obesity." (PMID 41148235, 2025). "This experimental setup generated a high signal/noise ratio, allowing comprehensive assessment of FAM20C’s role in AT dysfunction during obesity." (PMID 41148235, 2025). "Here we generated adipocyte‐specific FAM20C knockout mice to investigate the role of FAM20C in adipose tissue expansion and obesity." (PMID 39532808, 2024). "FAM20C expression was significantly higher in VIS than in SC ATs in individuals with obesity." (PMID 41148235, 2025). "The basis for the protection from diet-induced obesity remains unknown and could be due to postnatal development issues with adipocyte Fam20c ablation." (PMID 41148235, 2025). "It was unclear if deletion of adipocyte Fam20c can reverse established obesity and T2D." (PMID 41148235, 2025). "Pathway analysis of differentially phosphorylated proteins identified enrichment in integrin-mediated cell adhesion, insulin signaling, and regulation of the actin cytoskeleton, suggesting a critical role for FAM20C in these processes under pathological conditions of obesity." (PMID 41148235, 2025). "We next examined whether Fam20c influences insulin signaling in peripheral tissues during early obesity." (PMID 41148235, 2025). "Obesity induces Fam20c, a serine/threonine kinase, in adipocytes." (PMID 41148235, 2025). "Adipocyte‐specific FAM20C deletion conferred resistance to HFD‐induced obesity in mice." (PMID 39532808, 2024). "However, deletion of adipocyte Fam20c following short-term HFD decreases ATM populations and CLSs, indicating Fam20c promotes inflammatory adipose remodeling during early obesity." (PMID 41148235, 2025). "To investigate the relationship between FAM20C expression and metabolic dysfunction in humans, we analyzed FAM20C expression in a cross-sectional cohort comprising paired omental (VIS) and abdominal (SC) ATs from 1,480 individuals in the Leipzig Obesity Biobank (LOBB)." (PMID 41148235, 2025). "Fam20c expression was 2.5-, 3.4-, and 2.8-fold higher at 2, 4, and 15 weeks of HFD feeding, respectively, indicating an early and sustained induction throughout obesity." (PMID 41148235, 2025). "VIS WAT of genetically obese ob/ob mice fed a CD demonstrated 5-fold higher Fam20c expression compared with WT controls, suggesting that obesity rather than specific dietary factors drives Fam20c induction." (PMID 41148235, 2025). "Our results suggest that ablation of adipocyte FAM20C reduces basal lipolysis in obesity, likely due to improved insulin sensitivity, without affecting catecholamine responsiveness." (PMID 41148235, 2025). "The elevation of Fam20c in genetically obese ob/ob mice, independent of HFD, emphasizes its role as a response to obesity rather than to dietary lipid exposure, though it is possible that additional nutritional components may induce Fam20c." (PMID 41148235, 2025). "It is possible that the increased Fam20c in HFD-fed mice results from nutrient composition (e.g., lipid content) of the diet rather than obesity." (PMID 41148235, 2025).
Obesity (continued). "The shift toward smaller adipocytes in the absence of Fam20c likely reflects reduced adipocyte hypertrophy, which may limit the severity of VIS WAT dysfunction typically observed in obesity." (PMID 41148235, 2025).
Parkinson disease (2 papers, 2023 to 2024). A progressive degenerative disorder of the central nervous system characterized by loss of dopamine producing neurons in the substantia nigra and the presence of Lewy bodies in the substantia nigra and locus coeruleus. "The FAM20C protein targets and interactors identified are involved in different neural pathways, including neurodegenerative disorders such as Alzheimer’s and Parkinson’s diseases, and neurotransmitters such as enkephalin." (PMID 37240249, 2023).
prostate adenocarcinoma (2 papers, 2021). "Specifically, Fam20C expression levels were significantly elevated in HNSC (head and neck squamous carcinoma), LIHC (liver hepatocellular carcinoma), LUAD, PRAD (prostate adenocarcinoma), and THCA (thyroid carcinoma)." (PMID 33306121, 2021).
Ventricular arrhythmia (2 papers, 2018 to 2020). "Likewise, FAM20C-mediated phosphorylation of von Willebrand factor increased platelet adhesion, and lack of FAM20C phosphorylation of histidine-rich calcium binding protein causes ventricular arrhythmia." (PMID 32830861, 2020).
autoimmune disease (1 paper, 2021). A disorder resulting from loss of function or tissue destruction of an organ or multiple organs, arising from humoral or cellular immune responses of the individual to their own tissue constituents. "Eleven proteins (increased: ATP5B, CALML5, COLEC11, FCGBP, PLEK, PLXND1; decreased: APOB, ATP8B1, FAM20C, LOXL3, TIMD4) were significantly altered in bvFTD with autoimmune disease compared to those without autoimmune disease." (PMID 34539672, 2021).
behavioral variant frontotemporal dementia (1 paper, 2021). "One latest study reported the decreased expression of Fam20C in behavioral variant frontotemporal dementia (bvFTD) with autoimmune disease." (PMID 34988120, 2021).
bladder cancer (1 paper, 2021). "OPN, a substrate of Fam20C involved in cell differentiation, was overexpressed in bladder cancer tissues and OPN knockdown could suppress proliferation and invasion of human bladder cancer T24 cell via the JAK1/STAT1 pathway." (PMID 34988120, 2021).
bone osteosclerosis (1 paper, 2020). "This is partly in agreement with the bone osteosclerosis displayed by patients suffering RNS, which is a syndrome caused by the lack or reduced Fam20C activity." (PMID 33425910, 2020). "Indeed, bone osteosclerosis could be related to the lack or reduced activity of extracellular FAM20C in the developing osteoid." (PMID 33425910, 2020).
brain cancer (1 paper, 2021). A primary or metastatic malignant neoplasm affecting the brain. "Further, applying TCGA database of GEPIA to the analysis showed higher mRNA levels of Fam20C had an increased risk for shorter time for OS and DFS in most tumor types, including BLCA, CESC, and brain cancer (GBM and LGG), HNSC, and UVM." (PMID 33306121, 2021).
cognitive deficits (1 paper, 2026). "This study revealed that HIBD suppresses FAM20C in the hippocampal neurons on the ischemic side, which impairs neuronal differentiation and results in cognitive deficits after HIBD." (PMID 40511628, 2026). "The inhibition of FAM20C caused by HIBD affected cell differentiation and subsequently caused cognitive impairment." (PMID 40511628, 2026). "Collectively, NOR and MWM data suggest that FAM20C inhibition impairs learning and spatial memory, while its overexpression mitigates HIBD‐induced cognitive deficits." (PMID 40511628, 2026).
congestive heart failure (1 paper, 2018). Failure of the heart to pump a sufficient amount of blood to meet the needs of the body tissues, resulting in tissue congestion and edema. "By establishing Fam20C as a regulator during aging of myocardial form and function, this study portends an important molecular biologic role for Fam20C in the modern epidemic of congestive heart failure." (PMID 30520731, 2018).
developmental delay (1 paper, 2023). "Individuals with RNS can have developmental delay, intellectual disability, seizures, and structural brain defects, but little is known about FAM20C brain-target-protein dysregulation or about a potential pathogenesis associated with neurologic features." (PMID 37240249, 2023).
fibrosis (1 paper, 2018). the formation of excess fibrous connective tissue in an organ or tissue in a reparative or reactive process. "Using Masson’s Trichrome staining, we established that interstitial fibrosis was greatly increased in Fam20C cKO mice, while WT mice demonstrated no signs of fibrosis following 9 months of aging." (PMID 30520731, 2018).
gastric cancer (1 paper, 2021). A primary or metastatic malignant neoplasm involving the stomach. "Together with our finding that Fam20C impacted the prognosis in gastric cancer patients with lymph node metastasis, further provide an evidence about Fam20C expression might influence cancer cells migration." (PMID 33306121, 2021). "Further, enhanced expression of Fam20C can affect lymph node metastasis with gastric cancer patients, indicating that Fam20C could be used as a predictor of tumor metastasis." (PMID 33306121, 2021). "Thus we analyzed the relationship between the Fam20c expression and several characteristics of gastric cancer patients by using the Kaplan–Meier plotter database, which includes clinical features and pathological stages." (PMID 33306121, 2021).
iron deficiency (1 paper, 2021). "The mechanisms by which FAM20C is transcriptionally and functionally regulated remains to be elucidated, though studies suggest that changes in Gal-NAc-T3 and FAM20C activity or transcription seem to be regulated by iron, iron deficiency and elevated serum phosphate." (PMID 33716961, 2021).
lung carcinoma (1 paper, 2021). "Specifically, datasets of GEO were analyzed using PrognoScan showed that elevated Fam20C expression associated with worse prognosis in bladder, brain, colorectal, and lung cancers." (PMID 33306121, 2021).
lymphoma (1 paper, 2021). A malignant (clonal) proliferation of B- lymphocytes or T- lymphocytes which involves the lymph nodes, bone marrow and/or extranodal sites. "Based on the Oncomine data showed that Fam20C had a higher expression level in brain and CNS, breast, cervical, colorectal, esophageal, head and neck, lymphoma, and pancreatic cancers." (PMID 33306121, 2021). "In Oncomine database, compared with the normal tissues the result revealed higher expression of Fam20C in brain and CNS (central nervous system), breast, cervical, esophageal, head and neck, lymphoma, and pancreatic tumors." (PMID 33306121, 2021).
otosclerosis (1 paper, 2023). Formation of spongy bone in the labyrinth capsule which can progress toward the stapes (stapedial fixation) or anteriorly toward the cochlea leading to conductive, sensorineural, or mixed hearing loss. "Furthermore, MEPE, a classic FAM20C target, is involved in otosclerosis, affecting the bone remodeling of the otic capsule." (PMID 37240249, 2023).